SP110 (SP110 nuclear body protein)
Diseases named in the same sentence as SP110 in open-access papers (continued):
Sharing a sentence is not in itself a finding about the gene and the disease.
infection (13 papers, 2007 to 2024). The state of being infected such as from the introduction of a foreign agent such as serum, vaccine, antigenic substance or organism. "In SP110-knockdown macrophages, genes associated with oxidative phosphorylation were upregulated with infection." (PMID 39162523, 2024). "Further work will be required to clarify the functional impact of these genetic variants in SP110 on the response of human macrophages to infection." (PMID 25006821, 2014). "Downregulation of the transcriptional regulatory genes Sp110 and Sp140 in C3HeB/FeJ mice has been demonstrated to activate gene expression associated with inflammatory responses during M. tuberculosis infection, resulting in susceptibility to the infection." (PMID 39162523, 2024). "Additionally, SP110 is also as a susceptibility gene for infection with Mycobacterium avium subspecies paratuberculosis in cattle." (PMID 27622275, 2016). "The SP110 gene, also known as the intracellular pathogen resistance 1 (Ipr1) gene in mice, was first discovered at the super-susceptibility to tuberculosis 1 (sst1) locus on chromosome 1, where it plays a vital role in the host’s innate immune reaction to infections." (PMID 38891697, 2024). "In SP110-knockdown macrophages, infection with M. tuberculosis activated the expression of genes associated with oxidative phosphorylation." (PMID 39162523, 2024). "In SP110- and/or SP140-knockdown macrophages, genes associated with inflammatory responses were also upregulated upon infection with M. tuberculosis." (PMID 39162523, 2024). "We used RNA sequencing to analyze the global gene expression patterns in M. tuberculosis-infected lungs of B6, Sp110–/–, Sp140–/–, and B6.Sst1S mice at day 28 post-infection." (PMID 34151776, 2021). "At day 25 post-infection, Sp110–/– lungs resembled those of wild-type B6 mice and harbored fewer bacteria than the lungs of B6.Sst1S mice, similar to both the B6 and Sp110+/– littermates." (PMID 34151776, 2021). "When infected with M. tuberculosis, however, Sp140–/– mice exhibited high bacterial burdens in their lungs, similar to B6.Sst1S mice and significantly greater than B6, Sp110–/– or Sp140+/– littermate mice at day 28 post-infection." (PMID 34151776, 2021). "At 24 h post-infection, the cells were harvested and Sp110 expression was examined by quantitative (q) PCR and immunoblotting." (PMID 26912204, 2016). "Subsequent studies have identified a candidate gene within the sst1 locus designated as intracellular pathogen resistance 1 (also known as Sp110), and this gene regulates innate immunity to infection with Mtb8." (PMID 26912204, 2016). "SP110 is an interferon-responsive nuclear body protein with critical roles in cell cycling, apoptosis and immunity to infection." (PMID 25006821, 2014). "The mechanism by which A. phagocytophilum modulates the transcription of Sp110 to enhance infection of human HL-60 cells will require further study." (PMID 17883869, 2007). "While Sp110 mRNA levels increased concurrently with A. phagocytophilum infections in HL-60 cells, the silencing of Sp110 expression by RNA interference resulted in decreased infection levels." (PMID 17883869, 2007). "In SP110-knockdown macrophages, these genes were also induced by infection with M. tuberculosis." (PMID 39162523, 2024). "Additionally, Sp110 nuclear body protein, the human homologue of mouse Ipr1, plays important roles in the pathogenesis of infectious disease; Sp110 protein can facilitate the infection or replication of Anaplasma phagocytophilum and Epstein-Barr virus." (PMID 27622275, 2016). "Furthermore, silencing of Sp110 expression reduced pathogen infection/multiplication, thus suggesting that A. phagocytophilum can modulate the transcription of Sp110 to facilitate infection of human HL-60 cells." (PMID 17883869, 2007). "The human Sp110 and A. phagocytophilum msp4 mRNA levels were evaluated by real-time RT-PCR in infected human HL-60 cells sampled at 0, 12, 24, 48, 72 and 96 hours post-infection." (PMID 17883869, 2007).
infection (continued). "In the study reported herein, we hypothesized that Sp110 may be involved in the infection of human promyelocytic cells with A. phagocytophilum and used a combination of real-time RT-PCR and RNA interference (RNAi) to test this hypothesis." (PMID 17883869, 2007). "In this research, we hypothesized that Sp110 may be involved in the infection of human promyelocytic HL-60 cells with A. phagocytophilum." (PMID 17883869, 2007). "Expression of the remaining four genes (PARP9, SP110, SP100 and PRIC285) was unchanged by infection." (PMID 27533247, 2016). "Following infection with intracellular pathogens, the lungs of B6.Sst1S congenic mice lacking SP110 exhibited a significant increase in IL-1β levels." (PMID 38891697, 2024). "The transcription factors GABPA, ZNF579, SP110, and TSC22D2 were also induced after infection." (PMID 34777295, 2021). "Considering that cell viability and growth rate were not changed by SP110 and/or SP140 knockdown at 24 and 48 h p.i., ATP concentration in macrophages would not be affected by the depletion of SP110 and/or SP140 in the early infection period." (PMID 39162523, 2024).
tumor (10 papers, 2007 to 2025). "In contrast, Yunjie Duan (2023) reports lower SP110 expression in tumor-infiltrating immune cells, suggesting immune suppression that favors tumor growth." (PMID 41188771, 2025). "One hypothesis for this matter is SP110’s prognostic impact depends on the immune context of the PAAD tumor microenvironment (TME)." (PMID 41188771, 2025). "Metronomic CPA treatment also induced a core set of death-related genes that may be important for innate and/or adaptive immune activation by damaged tumor cells, including Sp110, Mx1, Mx2, Ebi3, Eomes, Tnfsf4, Gdf15, Ddx58, and Dhx58." (PMID 25952672, 2015). "The findings revealed positive correlations between the expression levels of SP100/SP110/SP140 and most tumor-infiltrating immune cells, including activated B cells, Tcm cells, CD8 T cells, and NKT cells." (PMID 37354211, 2023). "Here, we demonstrate a significant correlation between SP100, SP110, SP140, and SP140L genes’ expression and immune cell populations in the tumor microenvironment." (PMID 36614001, 2022). "Although the specific role of SP110 in OS is not detailed in the context, it is known that immune response pathways can significantly impact tumor progression." (PMID 40070565, 2025). "This systematic review underscores the dual oncogenic and tumor-suppressive roles of SP100 family proteins (SP100, SP110, SP140, SP140L) across 25 cancer types, shaped by context-dependent expression patterns, genetic/epigenetic alterations, and possible interactions with tumor microenvironments." (PMID 41188771, 2025).
cancer (4 papers, 2019 to 2025). A tumor composed of atypical neoplastic, often pleomorphic cells that invade other tissues. "The Speckled Protein 100 (SP100) family, comprising SP100, SP110, SP140, and SP140L, has emerged as a critical player in cancer biology due to their roles in transcriptional regulation, chromatin modification, and immune signaling." (PMID 41188771, 2025). "This systematic review analyzed 29 studies (2004–2024) to evaluate the dual roles of SP100 family proteins (SP100, SP110, SP140, SP140L) across 25 cancer types." (PMID 41188771, 2025). "After RAYYAN-assisted deduplication and screening, studies analyzing SP100, SP110, SP140, or SP140L alterations in human cancers (excluding cell lines studies) were included." (PMID 41188771, 2025).
bacterial infections (1 paper, 2021). "In particular, the loss of Sp110 (Ipr1) has long been proposed to explain the susceptibility of Sst1 mice to bacterial infections." (PMID 34151776, 2021). "Loss of Sp110 expression was proposed to account for the susceptibility of mice carrying the Sst1S haplotype to bacterial infections." (PMID 34151776, 2021). "Given that loss of Sp110 was not sufficient to explain the susceptibility of Sst1S mice to bacterial infections, we considered other explanations." (PMID 34151776, 2021). "To determine whether loss of Sp110 confers susceptibility to bacterial infections, we used CRISPR/Cas9 to target exon 3 of Sp110 to generate Sp110–/– mice on the C57BL/6 (B6) background." (PMID 34151776, 2021). "However, the causative role of Sp110 in conferring resistance to bacterial infections was not confirmed by the generation of Sp110-deficient B6 mice." (PMID 34151776, 2021).
SP110 also shares sentences with these, for which no sentence is quoted: hepatic veno-occlusive disease (3 papers); mastitis (2); adenocarcinoma (1); brucellosis (1); Combined immunodeficiencies (1); COVID-19 (1); Extra-Pulmonary Tuberculosis (1); hepatitis C virus infection (1); human granulocytic anaplasmosis (1); Hypertension (1); infectious disease (1); malaria (1); melanoma (1); metastatic carcinoma (1); Mycobacterium infection (1); oral cancer (1); ovarian carcinoma (1); pancreatic ductal carcinoma (1); Spinal Tuberculosis (1); tongue cancer (1).